APOBEC2 (apolipoprotein B mRNA editing enzyme catalytic subunit 2)
Description:
Probable C to U editing enzyme whose physiological substrate is not yet known. Does not display detectable apoB mRNA editing. Has a low intrinsic cytidine deaminase activity. May play a role in the epigenetic regulation of gene expression through the process of active DNA demethylation.
Synonyms: ARCD1; ARP1
Tractability: Small molecule: it has a high-quality binding pocket.
Gene: Protein-coding gene on chromosome 6 (41,053,201 to 41,064,891, forward strand). Ensembl gene ENSG00000124701.
Subcellular location (Human Protein Atlas): Nucleoplasm
Pathways (Reactome):
Metabolism of RNA: Formation of the Editosome; mRNA Editing: C to U Conversion
Gene Ontology:
Molecular function: cytidine deaminase activity; identical protein binding; RNA binding
Biological process: cytidine to uridine editing; positive regulation of gene expression via chromosomal CpG island demethylation
Cellular component: nucleoplasm; cytoplasm; nucleus
Genetic constraint (gnomAD): Loss-of-function variants: 14 observed, 20.17 expected, observed/expected ratio (o/e) 0.69, 90% interval 0.46 to 1.09. The upper end of that interval is the gene's LOEUF score, 1.09, which puts it in group 4 of 6, group 1 being the genes least tolerant of losing a copy. Missense variants: 304 observed, 287.7 expected, observed/expected ratio (o/e) 1.06, 90% interval 0.96 to 1.16. Synonymous variants: 127 observed, 118.17 expected, observed/expected ratio (o/e) 1.07, 90% interval 0.93 to 1.25.
Homologues: Orthologues: chimpanzee APOBEC2 (99% identical), macaque APOBEC2 (98% identical), dog APOBEC2 (95% identical), rabbit APOBEC2 (94% identical), pig APOBEC2 (92% identical), rat Apobec2 (92% identical), guinea pig APOBEC2 (91% identical), mouse Apobec2 (91% identical), zebrafish apobec2b (58% identical), zebrafish apobec2a (56% identical), tropical clawed frog apobec2 (52% identical). Paralogues in human: APOBEC3F (29% identical), APOBEC3B (28% identical), APOBEC3G (28% identical), APOBEC3D (28% identical), AICDA (27% identical), APOBEC3C (26% identical), APOBEC3A (25% identical), APOBEC3H (22% identical), APOBEC1 (20% identical).
Diseases named in the same sentence as APOBEC2 in open-access papers:
APOBEC2 is named in the same sentence as 16 diseases in open-access papers, as found by Europe PMC text mining. Sharing a sentence is not in itself a finding about the gene and the disease. The quoted sentences say what the papers report.
bladder cancer (1 paper, 2021). "For example, APOBEC2 expression in bladder cancer was associated with methylation of the 5′ UTR and the 1st exon of the DNA demethylase ALKBH2, whose product removes N1-meA and N3-meC (ρ = − 0.8687)." (PMID 33676569, 2021).
breast carcinoma (1 paper, 2015). "In addition, except the APOBEC3H gene, we found high DNA methylation levels of the remaining APOBEC members, including APOBEC1, APOBEC2, APOBEC3A, APOBEC4, and AICDA, in both HMEC and ER− breast cancer cells." (PMID 26682542, 2015). "For other APOBEC family members, they show either extremely low (median log2-transformed RPKM < 0) mRNA levels (including APOBEC3A, APOBEC3H, APOBEC1, APOBEC2, APOBEC4, and AICDA), or no obvious expression differences between ER+ and ER− breast cancers (including APOBEC3D, APOBEC3F, and APOBEC3G)." (PMID 26682542, 2015).
congenital myopathy (1 paper, 2018). "Our findings strongly suggest that Apobec2 is required for normal mitochondrial function to maintain skeletal muscle homeostasis and identify Apobec2 as a novel congenital myopathy gene and Apobec2−/− mice as a novel animal model of myopathies of unknown origin." (PMID 29127187, 2018).
gastric cancer (1 paper, 2024). A primary or metastatic malignant neoplasm involving the stomach. "Further studies are needed to clarify the expression of APOBEC2 in specific cells of gastric cancer based on scRNA-seq." (PMID 38166744, 2024). "The results of qRT-PCR demonstrated that APOBEC2 mRNA could be detected in gastric cancer cell line HGC27 and AG5." (PMID 38166744, 2024). "We noticed that the obvious difference of distribution pattern of APOBEC2 between in gastric cancer tissue and non-malignant tissues." (PMID 38166744, 2024). "Next, we investigated the expression of APOBEC2 protein in gastric cancer tissue and non-malignant tissues." (PMID 38166744, 2024).
hepatocellular carcinoma (1 paper, 2023). A malignant tumor that arises from hepatocytes. "HBV infection can induce the development of hepatocellular carcinoma by suppressing miR-122 expression and inducing the expression of miR-122 target gene APOBEC2, promoting the growth of HCC cells." (PMID 37274242, 2023).
liver cancer (1 paper, 2023). An epithelial or non-epithelial malignant neoplasm that arises from the liver. "Additionally, it was proposed that HBV accelerated the growth of liver cancer by promoting the expression of APOBEC2 by downregulating cellular miR-122." (PMID 36803831, 2023).
ovarian carcinoma (1 paper, 2016). A malignant neoplasm originating from the surface ovarian epithelium. "APOBEC1, APOBEC2 and DPPA3 mRNAs were not expressed or expressed at the detection limit in the ovarian cancer tissues of the herein investigated cohort of patients and therefore those variables were excluded from the univariate Cox regression and all subsequent analyses." (PMID 27527602, 2016).
skin tumours (1 paper, 2019). "The rabbit skin tumours induced via blood infection displayed decreased expression of SLN, TAC1, MYH8, PGAM2, and APOBEC2 and increased expression of SDRC7, KRT16, S100A9, IL36G, and FABP9, as seen in tumours induced by local infections." (PMID 31340720, 2019).
stomach adenocarcinoma (1 paper, 2024). "It showed that APOBEC2 transcripts were found to be significantly down regulated in stomach adenocarcinoma tissues compared to normal gastric tissues (P < 0.05)." (PMID 38166744, 2024). "Furthermore, we performed the analysis with cancer tissues in GEPIA database and revealed APOBEC2 gene expression is commonly down regulated in cancer tissues compared with normal tissues, suggesting APOBEC2 may be associated with the development of stomach adenocarcinoma." (PMID 38166744, 2024). "In this study, we noticed the frequency of APOBEC2 gene alteration in stomach adenocarcinoma using the database from cBioportal wanderer platform." (PMID 38166744, 2024). "Expression and prognosis value of APOBEC2 in stomach adenocarcinoma (STAD) remains unclear." (PMID 38166744, 2024). "The expression of APOBEC2 was found to be significantly down regulated in stomach adenocarcinoma tissue compared to the non-malignant fundic gland mucosa tissues (P < 0.0001)." (PMID 38166744, 2024). "The results obtained for 48 paired tissues revealed that APOBEC2 expression in stomach adenocarcinoma tissues was lower compared to that in the non-malignant gastric tissues (P < 0.0001)." (PMID 38166744, 2024). "We utilized the TCGA and GTEx datasets from GEPIA to explore the level of APOBEC2 mRNA in stomach adenocarcinoma tissues and adjacent non-malignant tissues." (PMID 38166744, 2024). "In addition, the results obtained for 8 paired tissues revealed that relative APOBEC2 mRNA in stomach adenocarcinoma tissues was lower compared to that in the non-malignant gastric tissues." (PMID 38166744, 2024).
cancer (5 papers, 2019 to 2025). A tumor composed of atypical neoplastic, often pleomorphic cells that invade other tissues. "Among them, APOBEC2 may be associated with nucleotide alterations in cancer-related gene transcripts, potentially promoting carcinogenesis." (PMID 39968416, 2025). "We also observed that some APOBECs exhibit a specifically high expression in some certain cancer types, e.g. APOBEC2 in THYM." (PMID 35673559, 2022). "Specifically, several genes including APOBEC2 and IL36γ were found to be significantly dysregulated in persistent rabbit tumors, consistent with profiles in HPV-associated cancers." (PMID 33584832, 2021). "Notably, 29 genes, including APOBEC2, GDNF, and PRELP, have been confirmed by existing literature to be associated with cancer development and progression." (PMID 39968416, 2025). "Notably, MONet identified 37 novel driver genes that were missed by other methods, including 29 genes such as APOBEC2, GDNF, and PRELP, which are corroborated by existing literature, underscoring their critical roles in cancer development and progression." (PMID 39968416, 2025). "We postulate that reduced expression of APOBEC2 may prevent or reduce C-to-U editing, as described for APOBEC3 for human papillomavirus, thereby minimizing hypermutations into the CRPV genome and facilitating cancer progression." (PMID 31340720, 2019).
myopathy (5 papers, 2012 to 2021). A disease of the muscle in which the muscle fibers do not function properly. "We conclude that Apobec2 deficiency causes mitochondrial defects that increase muscle mitophagy, leading to myopathy and atrophy." (PMID 29127187, 2018). "In summary, this study shows that mouse Apobec2 deficiency causes mitochondrial defects in skeletal muscle and induced mitophagy, both resulting in myopathy and muscle atrophy." (PMID 29127187, 2018). "We previously reported that Apobec2 deficiency in mice leads to a shift in muscle fiber type, myopathy, and diminished muscle mass." (PMID 29127187, 2018). "However, the mechanisms of myopathy caused by Apobec2 deficiency and its physiologic functions are unclear." (PMID 29127187, 2018). "Apobec2-deiffcient mice were characterized by many defects, including a reduction in body mass, mild myopathy, and increased proportion of slow muscle fibers in Soleus muscle." (PMID 34571854, 2021). "Mouse knockouts of Apobec2 tend to have a greater ratio of slow to fast twitch muscle, 15-20% reduction in body mass, and evidence of mild myopathy in aged mice." (PMID 25695797, 2015). "Thus, Apobec2−/− mice provide a novel mammalian model for understanding mitophagy in muscle regeneration and its links to myopathy." (PMID 29127187, 2018). "However, detailed analysis of these animals revealed a 15–20 % reduction in body mass from birth onwards, a clear histological evidence of a mild myopathy during aging, and a markedly increased ratio of slow to fast fibres in soleus Apobec2-/- muscles." (PMID 27075038, 2016). "Apobec2 is expressed in differentiating myocytes, and knockout mice are characterized by low muscle mass and nonlethal myopathy, while depletion of Apobec2 in zebrafish results in a dystrophic myopathy with deficiencies in lateral myocyte attachment and organization of the myosepta." (PMID 22400118, 2012).
infection (2 papers, 2018 to 2024). The state of being infected such as from the introduction of a foreign agent such as serum, vaccine, antigenic substance or organism. "Some studies suggested that the APOBEC2 might be involved in immune reactions to infection or inflammation." (PMID 38166744, 2024). "No significant change was observed with the expression of ADAR1–3, APOBEC1, APOBEC2, and APOBEC3A 3D, 3G, and 3H, whereas APOBEC3B, and 3C had a significant decrease, and APOBEC3F had a significant increase in A549 cells during the course of infection with H7N9." (PMID 29363430, 2018).
tumor (2 papers, 2019 to 2024). "In univariate Cox analysis, it is shown that OS and DFS in patients with STAD were associated with APOBEC2 expression status, size of tumor, neoplasm staging, and postoperative chemotherapy variables." (PMID 38166744, 2024). "Further studies are warranted to clarify associations between APOBEC2 and tumor microenvironment including immune cell infiltration." (PMID 38166744, 2024). "Recent observations have also linked the expression of APOBEC2 to tumors and indicated it in the regulation of tumor-related genes, including Eif4g2 and PTEN." (PMID 38166744, 2024). "Apolipoprotein B mRNA editing enzyme catalytic polypeptide-like 2 (APOBEC2) is associated with nucleotide alterations in the transcripts of tumor-related genes which are contributed to carcinogenesis." (PMID 38166744, 2024). "However, the significance of APOBEC2 protein expression in GC, especially in its association with tumor-infiltrating immune cells is unknown." (PMID 38166744, 2024). "We also explored the relationships of APOBEC2 with tumor size, location, serum CA19-9 levels and serum CEA levels in 496 cases, although statistical correlation was not evidenced." (PMID 38166744, 2024). "We detected expression of APOBEC2, infiltration of CD66b+ tumor-associated neutrophils and CD163+ tumor-associated macrophages in tissue microarrays by immunohistochemistry." (PMID 38166744, 2024). "Consistent with RNA-seq results, western blot analysis confirmed the increased expression of S100A9 and decreased expression of APOBEC2 in tumours induced by both routes of infections." (PMID 31340720, 2019). "Consequently, there are questions to be answered about the exact mechanism of correlation between APOBEC2 and tumor infiltrating immune cell." (PMID 38166744, 2024).
cardiovascular disease (1 paper, 2008). "Two of the genes we selected to this study, LCT and APOBEC2, have not been previously associated with molecular pathogenesis of cardiovascular disease." (PMID 18974842, 2008).
APOBEC2 also shares sentences with these, for which no sentence is quoted: cervical cancer (1 paper); congenital myasthenic syndrome (1).